JAK1 (Janus kinase 1)
Diseases named in the same sentence as JAK1 in open-access papers (continued):
Sharing a sentence is not in itself a finding about the gene and the disease.
pyoderma gangrenosum (3 papers, 2016 to 2025). An idiopathic, rapidly evolving, and severely debilitating disease occurring most commonly in association with chronic ulcerative colitis. "Tan and Tolkachjov (2024) reported that pyoderma gangrenosum lesions exhibit elevated levels of proinflammatory molecules, including various cytokines, interleukins, JAK-1, JAK-2, JAK-3, and interferon gamma." (PMID 40353091, 2025). "JAK1 and phosphorylated JAK1 were only significantly overexpressed in pyoderma gangrenosum." (PMID 37624299, 2023).
adenocarcinoma of the rectum (2 papers, 2020 to 2025). "Our study shows that multiple immune genes associated with ASCC3, including JAK1, NFKB1, SEMA5A, NR2C2, CNTF and CREB1, positively impact the prognosis of rectal adenocarcinoma patients." (PMID 40881169, 2025). "ASCC3 is a specific protective factor for rectal adenocarcinoma across various cancer types, particularly in digestive system cancers, and can synergize with several immune-related genes, including JAK1, NFKB1, SEMA5A, NR2C2, CNTF, and CREB1, to influence patient prognosis." (PMID 40881169, 2025).
allergic disease (2 papers, 2015 to 2022). An immune response that occurs following re-exposure to an innocuous antigen, and that requires the presence of existing antibodies against that antigen. "This work highlights the role of JAK1 signaling in atopic immune dysregulation and the clinical impact of JAK1/2 inhibition in treating eosinophilic and allergic disease." (PMID 36546480, 2022). "Furthermore, enhanced JAK1 signaling impacts numerous cell types, including those of nonhematopoietic lineage that can also play important roles in the pathophysiology of allergic disease, such as the epithelial barrier." (PMID 36546480, 2022). "Despite the established role for JAK1 in IL-6 and IFN signaling, we determined that heightened JAK1 signaling drives a Th2 phenotype, explaining the clinical findings of severe allergic disease in JAK1GOF patients." (PMID 36546480, 2022).
allergic rhinitis (2 papers, 2021 to 2022). Inflammation of the nasal mucous membranes caused by an IgE-mediated response to external allergens. "It has been shown that inhibition of Wnt/β-catenin and JAK1/STAT3 signalings could suppress the development of allergic rhinitis." (PMID 34315133, 2021). "IL-9 neutralizing antibody plays a therapeutic role in mice with allergic rhinitis, possibly through the TSLP-OX40/OX40L signal pathway and JAK1/2-STAT5 signal." (PMID 36172190, 2022). "After using an IL-9 neutralizing antibody, the expression of JAK1/2 and STAT5 decreased significantly compared to the allergic rhinitis group, and the degree of phosphorylation also decreased significantly." (PMID 36172190, 2022). "IL-9 neutralizing antibody has a good therapeutic effect on the mouse model of allergic rhinitis, which may be related to the TSLP-OX40/OX40L pathway and JAK1/2-STAT5 signaling." (PMID 36172190, 2022).
astrocytoma (2 papers, 2017 to 2022). "In previous studies, PIBF (200 ng/mL) increased the number of astrocytoma cells through the activation of the IL-4Rα/JAK1/STAT6 pathway." (PMID 28168193, 2017).
autism (2 papers, 2021 to 2023). Persistent deficits in social interaction and communication and interaction as well as a markedly restricted repertoire of activity and interest as well as repetitive patterns of behavior. "Our patient had autism and a moderate learning disability, but these characteristics were not present in the other two reports of individuals with gain-of-function JAK1 mutations." (PMID 35046931, 2021). "The upregulation of JAK-STAT signaling has also been noted in autistic children, but there is insufficient evidence at present to establish reliable causal links between aberrant IL-6, JAK1 dysfunctions and autism from this data." (PMID 35046931, 2021). "However, strong evidence was lacking to establish the causation between IL-6 and JAK1 abnormalities with autism." (PMID 38026692, 2023). "Adding to the significance of JAK1, researchers have observed an upregulation of JAK–STAT signaling in children with autism, further emphasizing its importance." (PMID 38026692, 2023).
CANDLE syndrome (2 papers, 2015 to 2023). "A patient with AA was enrolled in a clinical trial to examine the efficacy of baricitinib, a JAK1/2 inhibitor, to treat concomitant CANDLE syndrome." (PMID 26137574, 2015). "Here, we describe a patient enrolled in a clinical trial of baricitinib, an oral JAK inhibitor with relative selectivity for JAK1 and JAK2, for CANDLE syndrome who experienced dramatic resolution of his AA." (PMID 26137574, 2015).
cardiomyopathies (2 papers, 2025). "Cardiomyopathy in Jak1-deficient hearts is characterized by left ventricular dilation, systolic dysfunction, and substantial cardiac fibrosis." (PMID 40744288, 2025). "Moreover, JAK1 and IFNA16/IFNA14 can be used for constructing models to accurately identify the two cardiomyopathies." (PMID 39704101, 2025). "Cardiomyopathy in aged mice lacking cardiomyocyte JAK1 was characterized by substantial myocardial fibrosis." (PMID 40744288, 2025).
cholangitis (2 papers, 2022 to 2024). An acute or chronic inflammatory process affecting the biliary tract. "We hypothesized that the downregulation of IFN signaling pathways with a JAK1/2 inhibitor would inhibit the development and progression of cholangitis." (PMID 36042351, 2022). "Additionally, JAK1 was associated with essential tremor (333.1, P = 1.03 × 10−2) and RB1CC1 displayed an association with cholangitis (575.1, P = 1.02 × 10−2) and IL6ST with noninfectious gastroenteritis in UK Biobank (558, P = 3.14 × 10−2)." (PMID 38741190, 2024).
chromophobe renal cell carcinoma (2 papers, 2020 to 2025). Chromophobe renal cell carcinoma is a rare subtype of renal cell carcinoma, originating from the intercalating cells of the collecting ducts and macroscopically manifesting as a well-circumscribed, highly lobulated, solid tumor that is usually diagnosed at an early stage. "Moreover, Kaplan-Meier survival analysis showed that higher expression of STING/JAK1 or STING/ISGs in vascular endothelial cells was associated with better overall survival rate in patients with kidney chromophobe (KICH), kidney renal clear cell carcinoma (KIRC), and soft tissue sarcoma (SARC)." (PMID 39817453, 2025).
Chronic myeloid leukemia (2 papers, 2016 to 2021). "Ruxolitinib, the first JAKinib approved by the United States Food and Drug Administration (FDA), is a potent inhibitor of JAK1 and JAK2, used for primary myelofibrosis and its effects have been also studied in MDS, AML, ALL, chronic myelomonocytic leukemia (CMML) and chronic myeloid leukemia (CML)." (PMID 34055801, 2021).
chronic obstructive pulmonary disease (2 papers, 2015 to 2022). A chronic and progressive lung disorder characterized by the loss of elasticity of the bronchial tree and the air sacs, destruction of the air sacs wall, thickening of the bronchial wall, and mucous accumulation in the bronchial tree. "The Janus tyrosine kinase/signal transducer and activator of transcription (JAK1/STAT3) pathway plays an important role in the process of acute exacerbation of chronic obstructive pulmonary disease (AECOPD)." (PMID 35571736, 2022).
cicatricial alopecia (2 papers, 2025). Scarring hair loss, also known as cicatricial alopecia, is the loss of hair which is accompanied with scarring. "A phase 2a study evaluating the efficacy of oral dual JAK1/tyrosine kinase 2 inhibitor brepocitinib in cicatricial alopecias found significant downregulation of inflammatory biomarkers, including CCL5, and demonstrated a favorable safety profile." (PMID 40778340, 2025).
Cirrhosis (2 papers, 2022 to 2025). A chronic disorder of the liver in which liver tissue becomes scarred and is partially replaced by regenerative nodules and fibrotic tissue resulting in loss of liver function. "Future trials using a JAK1/2 inhibitor may be more beneficial in earlier stages of PBC before cirrhosis and assessment of treatment response using markers of inflammation." (PMID 39859319, 2025).
coronary artery disease (2 papers, 2019 to 2022). "Similar JAK1/2 inhibitors have recently received an FDA safety warning based in part on possibly increased coronary artery disease and thrombotic risk." (PMID 35587375, 2022).
developmental delay (2 papers, 2021 to 2022). "The sole patient with homozygous loss-of-function JAK1 mutations did have mild developmental delay." (PMID 35046931, 2021). "In 2016, two homozygous variants of the pseudokinase domain in JAK1 were identified in a patient of Pakistani descent who had a mycobacterial infection and a history of recurrent viral, fungal, and parasitic skin infections since infancy along with global developmental delay." (PMID 36569938, 2022).
diffuse large B-cell lymphoma (2 papers, 2019 to 2021). "The H3Y41 locus may also be phosphorylated by JAK1, thus regulating nearly 3000 proliferation- and survival-associated genes in activated B cell-like diffuse large B cell lymphoma (ABC-DLBCL), including IRF4, MYD88 and MYC." (PMID 34680295, 2021).
endometriosis (2 papers, 2024 to 2025). The growth of functional endometrial tissue in anatomic sites outside the uterine body. "In stark contrast, FMT from endometriosis patients exacerbates disease progression by impairing microbial ecology, diminishing acetate production, failing to activate JAK1/STAT3, promoting M2 polarisation and disrupting gut barrier function." (PMID 40739711, 2025). "A key mediator of the type I IFN pathway, JAK1, is significantly upregulated in endometriotic lesions compared to the eutopic endometrium of endometriosis patients." (PMID 39125716, 2024). "This suggests that the IFNA/IFNAR2/JAK1 signaling pathway is essential in endometriosis progression." (PMID 39125716, 2024). "Furthermore, JAK1, a critical component of type I IFN signaling, shows increased expression in endometriosis stromal cells compared to endometrial cells from individuals without endometriosis." (PMID 39125716, 2024).
enteritis (2 papers, 2022 to 2024). Inflammation of the small intestine. "Introduction of Baricitinib as a JAK1/ 2 kinase inhibitor alongside traditional immunosuppressive agents successfully reduced the symptoms of enteritis by blocking the inflammogenic effects of type 1 interferonopathy in a case of tricohepatoenteric syndrome diagnosed in a 5-year-old boy." (PMID 37168478, 2022).
enteropathy-associated T-cell lymphoma (2 papers, 2024 to 2025). An uncommon mature T-cell lymphoma of intraepithelial lymphocytes. "The JAK1 and STAT3 gene mutations are observed in 90% of Enteropathy-associated T-cell lymphoma (EATL) patients and 80% of refractory celiac disease type II (RCD2) patients." (PMID 40046420, 2025).
experimental autoimmune encephalomyelitis (2 papers, 2024 to 2025). An autoimmune demyelinating disease of the central nervous system that is produced experimentally in animals by the injection of homogenized brain or spinal cord in Freund's adjuvant. "In animal models of experimental autoimmune encephalomyelitis (EAE), baricitinib was confirmed to act as a JAK1/2 inhibitor, delays disease onset, mitigates symptom severity, and inhibits Th1/Th17 polarization alongside STAT1/3/4 phosphorylation." (PMID 41585231, 2025).
folliculitis (2 papers, 2024 to 2025). Inflammation of the hair follicles. "Similar to the results from the EGFRΔEgr2 folliculitis model, topical JAK1/2 inhibition re-established skin barrier function, restored visible hair growth and reduced MHC expression on the treated side (right side) of the mice." (PMID 39521937, 2024).
food allergies (2 papers, 2022 to 2025). "IL-4R can utilize Janus kinase 1 (JAK1) for signal transduction in food allergies." (PMID 40005151, 2025).
fungal infection (2 papers, 2024 to 2025). "Clinicians should be made aware of the heightened risk of relapse of fungal infections in patients on JAK1 and JAK2 inhibitors." (PMID 41164159, 2025). "As the U.S. Food and Drug Administration expands approval for JAK inhibitor treatments for numerous diseases, clinicians must be aware of the increased risk of invasive fungal infections in JAK1 inhibitors." (PMID 41164159, 2025). "Reported endemic mycoses associated with JAK1/JAK2 inhibitors and clinical presentations." (PMID 41164159, 2025). "This suggests that the JAK1-STAT pathway plays a pivotal role in defense against fungal infections." (PMID 41164159, 2025). "Consistently, we found that the loss of FcεR1γ significantly impaired the phosphorylation of JAK1 and JAK3 in ILC3s in response to the fungal infection." (PMID 39013884, 2024). "Notably, the selective JAK1 inhibitor, itacitinib, was discontinued after phase 3 clinical trials due to its ineffectiveness in treatment of GVHD, and there are no current data on the risks of fungal infections with this drug." (PMID 41164159, 2025).
Granuloma (2 papers, 2025). A compact, organized collection of mature mononuclear phagocytes, which may be but is not necessarily accompanied by accessory features such as necrosis. "Key cytokines implicated in granuloma pathogenesis, such as IFN-γ and IL-6, signal through their respective JAK-STAT axes (JAK1/JAK2-STAT1 and JAK1/JAK2/TYK2-STAT3)." (PMID 41459541, 2025).
gynecological cancer (2 papers, 2016 to 2019). "As described for gynecological cancer cells bearing somatic JAK1 mutations, we also observed lower surface MHC I expression by JAK1-deficient hTERT urothelial cells compared with control cells at baseline." (PMID 31552026, 2019).
head and neck cancer (2 papers, 2021 to 2024). A primary or metastatic malignant neoplasm affecting the head and neck. "We then hypothesised that the 5 upregulated genes (namely, ATPase phospholipid transporting 8A1 [ATP8A1], BAHD1, cathepsin [CTSD], janus kinase 1 [JAK1], and myosin regulatory light chain interacting protein [MYLIP]) play a role in radioresistance of prostate and head and neck cancers." (PMID 39719436, 2024).
interstitial lung disease (2 papers, 2023 to 2024). A diverse group of lung diseases that affect the lung parenchyma. "Tofacitinib, a selective inhibitor of JAK1 and/or JAK3, is considered to alleviate the pulmonary condition of primary Sjögren’s syndrome (pSS)-associated interstitial lung disease (ILD) through its anti-inflammatory and antifibrotic effects." (PMID 38007449, 2023).
intracerebral hemorrhage (2 papers, 2022 to 2024). A cerebrovascular disorder characterized by bleeding into one or both cerebral hemispheres including the basal ganglia and the cerebral cortex. "IL-4 may partially promote M2 microglia/macrophage polarization through the JAK1/STAT6 pathway, therefore reducing neuroinflammation after intracerebral hemorrhage." (PMID 35204186, 2022).
ischemic stroke (2 papers, 2019 to 2023). A stroke disorder caused by obstruction of blood flow to the brain, due to thrombotic (local blood clot formation) or embolic (due to a blood clot or other material traveling from another site) event. "Therefore, specific inhibition of the IL‐6/JAK‐1/pSTAT3 pathway in astrocytes is a potential therapeutic approach to alleviate the progression of ischemic stroke caused by folic acid deficiency." (PMID 36794521, 2023). "Our study findings further suggest that not only Jak1, but also Jak2 may be involved in gliogenesis and astrocyte differentiation from neural stem cells after ischemic stroke." (PMID 31733648, 2019).
liver dysfunction (2 papers, 2021 to 2023). "The mutation of JAK1 was concluded to be associated with an autoinflammatory skin disease associated with liver dysfunction and ASD." (PMID 38026692, 2023).
lymphopenia (2 papers, 2024 to 2025). Reduction in the number of lymphocytes. "Modeling based on IL-2 IC50 predicts up to 94% average daily inhibition at clinical dosage, which would suggest severe lymphopenia to be more prevalent with JAK1,2,3 inhibitor use." (PMID 39403378, 2024). "Reductions in NK and T cells, increases in B cells, and lymphopenia are on-target effects of JAK1,2,3 inhibitors but not deucravacitinib." (PMID 39403378, 2024).
meningioma (2 papers, 2013 to 2020). A generally slow growing tumor attached to the dura mater. "The effects of cucurbitacin I on cerebrospinal fluid stimulation of meningioma cell DNA synthesis phosphorylation/activation of JAK1, STAT3, pMEK1/2, p44/42MAPK, Akt, mTOR, Rb and caspase 3 activation were analyzed in human leptomeningeal and meningioma cells." (PMID 24188277, 2013).
multiple sclerosis (2 papers, 2016 to 2025). A progressive autoimmune disorder affecting the central nervous system resulting in demyelination. "We determined whether the myelofibrosis drug ruxolitinib, an inhibitor of Janus kinases 1/2 (JAK1 and JAK2), could interact with the multiple sclerosis drug dimethyl-fumarate (DMF) to kill tumor cells; studies used the in vivo active form of the drug, mono-methyl fumarate (MMF)." (PMID 26981780, 2016).
myeloid neoplasm (2 papers, 2021 to 2025). Proliferation of myeloid cells originating from a primitive stem cell. "Notably, the JAK1/2 inhibitor ruxolitinib has shown efficacy in patients with CSF3R T618I‐positive CNL and anecdotal benefit in other CSF3R‐mutated myeloid neoplasms." (PMID 41423432, 2025).
parasitemia (2 papers, 2015 to 2024). "Here, we observed that both Ara-LAM and PGN induced the IFN-γRα associated JAK1/2-STAT1 signaling cascade in parasitized macrophages resulted in diminished parasitemia, both in vitro and in vivo, but Ara-LAM was found more potent." (PMID 25658110, 2015). "Given the wealth of data on JAK2 inhibitors and the fact that one such inhibitor, Ruxolitinib (targets JAK1/2) has a European Union patent that is expected to expire in August 2027 and the US patent is expected to expire in December 2027 offers opportunity for use in parasitic disease treatment." (PMID 39817173, 2024).
Parkinson disease (2 papers, 2024 to 2025). A progressive degenerative disorder of the central nervous system characterized by loss of dopamine producing neurons in the substantia nigra and the presence of Lewy bodies in the substantia nigra and locus coeruleus. "Recent studies show that α-synuclein can activate the JAK-STAT pathway in microglia and macrophages of a model of Parkinson's disease, while the JAK1/2 inhibitor, AZD1480, attenuates the degeneration of dopaminergic neurons." (PMID 39385706, 2025). "In a Parkinson’s disease rat model, inhibitors of JAK1 and JAK2, such as AZD1480, reduced microglial proliferation and macrophage infiltration and decreased MHC class II expression." (PMID 39229261, 2024).
periodontitis (2 papers, 2025). An acute or chronic inflammatory process that affects the tissues that surround and support the teeth. "Mangiferin, a xanthonoid polyphenol with anti-inflammatory properties, had limited reported evidence regarding its JAK1-targeting activity Periodontitis, the most prevalent oral infection in humans and primary cause of adult tooth loss, has been investigated in murine models." (PMID 40841966, 2025). "The efficacy of different JAK inhibitors (JAK1‐3i vs. JAK3i) in preventing the pathological changes associated with ligature‐induced periodontitis was evaluated, and the results did not demonstrate a clear superiority of either compound." (PMID 41041963, 2025). "This study aimed to investigate the role of Janus kinase (JAK) signaling in the pathogenesis of periodontitis by evaluating the effects of pharmacological inhibition of JAK isoforms (JAK1 and JAK3) on periodontal inflammation and ligature‐induced alveolar bone loss." (PMID 41041963, 2025). "Inhibition of the JAK pathway using JAK1‐3 and JAK3 inhibitors significantly modulated immune responses and attenuated tissue degradation in a rat model of experimentally induced periodontitis." (PMID 41041963, 2025). "Mangiferin treatment significantly reduced the phosphorylation levels of JAK1, STAT1 and STAT3 in gingival epithelia of periodontitis mice." (PMID 40841966, 2025).